ACTN4 (actinin alpha 4)
Diseases named in the same sentence as ACTN4 in open-access papers (continued):
Sharing a sentence is not in itself a finding about the gene and the disease.
tumor (53 papers, 2012 to 2025). "Studies have shown that ACTN4, one of the actin‐binding family, was a non‐actin protein associated with tumor development, invasion, and metastasis." (PMID 38764726, 2024). "Based on the previous reports on mutanomes of B16F10 tumor, we selected two of the somatic mutations of Pbk and Actn4 as neoantigens to test in our study." (PMID 36311701, 2022). "Loss and gain of function studies have revealed that ACTN4 promotes tumor oncogenesis and metastasis." (PMID 34546849, 2021). "In the actin-binding protein family, the ACTN4 protein, which was described by Honda and other researchers in the early stage and is considered a nonmuscle α-actinin closely linked to the migration ability of tumor cells, has attracted much attention." (PMID 39931061, 2025). "Furthermore, high ACTN4 expression was significantly associated with clinical stage, tumor grade, and lymph node status." (PMID 39061201, 2024). "This consistency reinforces the potential role of ACTN4 amplification and subsequent actinin‐4 expression in driving the aggressive characteristics of this tumor subtype." (PMID 41218617, 2025). "PDLIM1 and ACTN4 were mainly expressed in endothelial cells, fibroblasts, smooth muscle cells, and tumor/epithelial cells." (PMID 38694875, 2024). "Previous studies have shown that ACTN4 promotes tumor cell proliferation, migration, and invasion through the NF-κB pathway in osteosarcoma and increases the radioresistance and invasiveness of breast cancer cells through the AKT pathway." (PMID 37626047, 2023). "While ACTN4 suppression decreased the aggressiveness of tumor cells, overexpression of ACTN4 enhanced cell motility and dissemination." (PMID 38107139, 2023). "For ACTN4, our results indicated that its expression tends to either decrease or remain unchanged in tumor tissues compared to adjacent normal tissues (ANTs) or precancerous tissues across multiple HNSCC cohorts." (PMID 38057867, 2023). "The Wilcoxon rank-sum test showed significantly different expressions in 22 DRGs, except for ACTN4, between normal and tumor tissues." (PMID 37552140, 2023). "To further test the in vivo impact of TP73-AS1/miR-125a-3p/ACTN4 axis, we set up the subcutaneous xenograft tumor model with SPC-A1 treated with sh-TP73-AS1." (PMID 36118078, 2022). "In detail, the interaction between NHERF1 and ACTN4 increased ACTN4 ubiquitination and degradation by the proteasome, impacting actin cytoskeleton organization and tumor cell migration and invasion." (PMID 35223518, 2022). "More importantly, xenograft assays demonstrated that TP73-AS1 KD inhibits tumor growth via modulating the miR-125a-3p/ACTN4 axis, as expanded miR-125a-3p level and diminished ACTN4 level were observed in tumor tissues." (PMID 36118078, 2022). "In this review, we discuss the role of ACTN4 in the process of tumor progression and the usefulness of ACTN4 as a potential biomarker for selecting patients most likely to benefit from adjuvant chemotherapy." (PMID 36139525, 2022). "For example, ACTN4 is involved in the formation of F-actin and the regulation of cell migration and tumor invasion, and DBN1 plays a role in cell migration and actin polymerization." (PMID 34726485, 2021). "These proteins (THBS1, FBLN1, EDIL3, QSOX1, ACTN4, MMP3) also displayed differential mRNA expression in CRC compared to healthy intestine in the CRC TCGA dataset, and are implicated in tumour growth and metastasis regulation." (PMID 33802764, 2021). "Strikingly, we found that ACTN4 upregulation significantly promoted tumor growth, while OTUD3 knockdown effectively inhibited this trend." (PMID 34380780, 2021). "Inhibition of ACTN4 decreased the formation of cell filopodia and therefore suppressed tumor cell migration." (PMID 33033380, 2020). "As an actin-binding protein, ACTN4 is closely related to enhancing cell viability and tumor invasion and metastasis." (PMID 32855746, 2020).
tumor (continued). "This further supported the data that high ACTN4 levels were involved in the NSCLC recurrence through tumor metastases." (PMID 31766144, 2019). "While the expression of ACTN4 was shown to be elevated in certain types of tumors, suggesting its role as an oncogene, in other cases it has been shown to exhibit tumor suppressor activity." (PMID 31766144, 2019). "For example, ACTN4 and 67LR were found to be up-regulated from stage I to III ESCC, where ACTN4 was associated with advanced tumor stage and lymph node metastasis whereas 67LR was correlated with an advanced tumor stage." (PMID 27053248, 2016). "It has been suggested that ACTN4 is indispensable for mononuclear phagocyte response both in inflammation and tumor invasion processes." (PMID 25885339, 2015). "The correlation analysis between CNI and protein expression in ADCC (gray bars) revealed that although 85.7% of ADCCs had strong expression (+3) or moderate expression (+2) of actinin-4 protein, CNI of ACTN4 was recognized in only one tumor." (PMID 24574362, 2014). "Among these, we found some tumor suppressor genes (e.g. H19, ACTN4) that were down-regulated and some genes related to tumor progression and metastasis formation (e.g. ENPP2, GRIA3, TPM3) that were up-regulated." (PMID 23049808, 2012). "Even though the roles of ACTN4 in tumors reported in the literature are contradictory our data are in agreement with those of authors who demonstrated the role of ACTN4 gene in suppressing tumorigenicity in different tumor types." (PMID 23049808, 2012). "Therefore, we sought to reveal the mechanism of PHKA1‐AS1 in promoting tumor progression by exploring its ability to regulate the ubiquitination and degradation process of ACTN4." (PMID 38764726, 2024). "The metastatic potential of tumor cells decreases when ACTN4 is downregulated in breast cancer." (PMID 35568845, 2022). "TP73-AS1 inhibition could also inhibit the NSCLC tumor growth and correspondingly regulated the expression of miR-125a-3p and ACTN4 in the tumor xenograft model." (PMID 36118078, 2022). "ACTN4 might exert multiple functions in tumor tissues, which could also be related to the degree of malignancy of other tumors." (PMID 36118078, 2022). "ACTN4 (Actinin Alpha 4), one of the actin-binding protein families, is involved in the regulation of cytoskeletal structure and is closely related to epithelial-mesenchymal transition and metastasis of tumor cells." (PMID 35568845, 2022). "ACTN4 also participates in the proliferation of tumor cells." (PMID 35568845, 2022). "The ACTN4 gene is ubiquitously expressed in both normal and tumor cells." (PMID 30879239, 2020). "Therefore, ACTN4 can be a therapeutic target to prevent tumor survival, metastasis, and recurrence of PCa." (PMID 33363146, 2020). "Since the β-catenin signaling pathway is critical for tumor growth and metastasis, we examined whether ACTN4 influences the β-catenin activation in PCa." (PMID 33363146, 2020). "While the molecular mechanisms responsible for this phenotype are not well understood and require further investigation, it is accepted that mechanistically ACTN4 affects cell cycle and the migration of cells, which indicates its importance in tumor development and metastasis." (PMID 31766144, 2019). "In this case, investigations of ACTN4 interactions may become a valuable asset to predictive value by combining its use with other tumor-specific markers." (PMID 31766144, 2019). "Hence, considering both ACTN4 gene dosage and its expression makes them more reliable prediction factors for various aspects of tumor development." (PMID 31766144, 2019).
tumor (continued). "ACTN4 thus functions as a promoter for many tumor types and could be an important target protein in drug development." (PMID 29143101, 2018). "The overlap of ACTN4 amplification with aggressive histological subtypes makes it difficult to definitively determine whether ACTN4 amplification is an independent driver of tumor aggressiveness or a surrogate marker of this phenotype." (PMID 41218617, 2025). "Furthermore, lower ACTN4 expression was associated with significantly worse overall survival in HNSCC patients, suggesting that ACTN4 may exert a tumor-suppressive role in HNSCC." (PMID 38057867, 2023). "Therefore, it is logically rational to deduce that ACTN1 could play a role similar to that of ACTN4 in tumor development." (PMID 34546849, 2021). "In addition, we demonstrated that ACTN4 induces tumor growth after castration in vivo." (PMID 33363146, 2020). "Interestingly, ACTN4 has been reported to be present in exosomes from tumor (mesothelioma) cells." (PMID 29143101, 2018). "Moreover, tumor formation in the nude mice demonstrated that ACTN4 knockdown could significantly inhibit tumor growth and lung metastasis." (PMID 29197410, 2017). "In addition, although multivariate analysis revealed that CNI of ACTN4 and vascular invasion were independent risk factors for tumor death, histological grade did not remain as an independent risk factor." (PMID 24574362, 2014). "Through its PHD domain, PHF23 interacts with Alpha-actinin-4 (ACTN4), subsequently activating the ERK signaling pathway to stimulate tumor cell proliferation and metastasis." (PMID 41268576, 2025). "The results revealed that the expression of ACTN4 and LCN2 was positive in the cytoplasm and partly in the nucleus and that the expression level of ACTN4 was low, whereas the expression level of LCN2 was high in tumor tissue." (PMID 39931061, 2025). "ACTN4 has a poor prognosis with high expression in six tumor types (GBMLGG, LGG, MESO, PAAD, LUAD, LAML) and a poor prognosis with low expression in two tumor types (KIPAN, KIRC)." (PMID 39329952, 2024). "The biomarker ACTN4 exhibits promise for the diagnosis and management of LUAD, given its correlation with tumor immune infiltration and m6A modification." (PMID 38517776, 2024). "All six proteins are differentially expressed in malignant vs. healthy tissue in CRC (FBLN1, MMP3, ACTN4, THBS1, EDIL3) or other tumour entities (QSOX1)." (PMID 33802764, 2021). "Mechanistically, TRIP13 interacted with ACTN4 and positively regulated its expression, thus activating the AKT/mTOR pathway to drive tumor progression." (PMID 31533816, 2019). "This up-regulation expands to other potential tumor markers including A1AT1, tropomyosin-4, TUBB3, ACTN4, DDX3X, LMNB1, PARP and vimentin." (PMID 29109428, 2017). "The clinical and preclinical data suggested that ACTN4 is a potential predictive biomarker for efficacy of ADJ in stage-IB/II patients with NSCLC, by reflecting the metastatic potential of tumor cells." (PMID 27121206, 2016). "These genes regulated by ACTN4 were vital in EMT, which led to tumor progression." (PMID 38764726, 2024). "Some recent studies have discovered that non-muscle α-actinins occupy positions in tumor genesis and development, which is mainly supposed by deregulated ACTN4 in many kinds of cancer tissues related to normal tissue counterparts." (PMID 34546849, 2021). "There was no additive inhibitory effects on tumor growth when combining EA with ACTN4 knockdown." (PMID 29197410, 2017).
kidney disease (12 papers, 2009 to 2025). "For example, the kidney disease causing mutation, ACTN4-K225E, increased the binding affinity of ACTN4 for actin, leading to increased actin filament aggregation, providing an explanation for the disease." (PMID 27287556, 2016). "The identification of ACTN4 mutations as a cause of human kidney disease demonstrates a key cellular pathway by which alterations in cytoskeletal behavior can mediate kidney disease." (PMID 26301083, 2015). "Individuals with kidney disease-associated ACTN4 mutations tend to have mild to moderate proteinuria, with many developing decreased kidney function progressing to end stage kidney disease." (PMID 26301083, 2015). "Missense mutations in ACTN1, ACTN2 and ACTN4 cause dominantly inherited platelet, cardiac and renal disorders respectively, while a nonsense mutation in ACTN3 seems to have been beneficial during the recent evolution of some human populations." (PMID 26312134, 2015). "Altogether, homozygous Actn4 KO mice demonstrated the importance of the expression level of Actn4 in kidney disease." (PMID 26301083, 2015). "Mutations in ACTN4 are inherited in an autosomal-dominant fashion and mostly lead to FSGS and ESRD in adult patients, although several reports including this manuscript describe patients that develop severe kidney disease at a rather young age." (PMID 36815115, 2022). "Here we review the studies relevant to ACTN4 and its role in mediating kidney disease." (PMID 26301083, 2015). "The identified ACTN4 variant p.M240T could not be found in either large genome databases (gnomAD22 and HGMD mutational databases [HGMD professional 2022.2]) or our local rare kidney disease database." (PMID 36815115, 2022).
infection (6 papers, 2014 to 2018). The state of being infected such as from the introduction of a foreign agent such as serum, vaccine, antigenic substance or organism. "Following immunoprecipitation with the anti-ACTN4 antibody, we found binding of EGFR to ACTN4 increased significantly in response to PCN033 infection, while contrastingly, the association of cellular actin molecules with ACTN4 decreased markedly." (PMID 30687645, 2018). "Subsequently, co-immunoprecipitation (Co-IP) experiments were applied to PCN033-infected cell lysates using anti-EGFR antibody, and increased binding of ACTN4 to EGFR was observed during the PCN033 infection." (PMID 30687645, 2018). "The result showed that CyD treatment largely increased the EGFR recruitment of ACTN4 during the infection, which suggested that the infection-activated EGFR recruitment of ACTN4 was a direct interaction and independent of actin." (PMID 30687645, 2018). "After pretreating the cells with EGFR inhibitor AG1478, the infection-induced binding of ACTN4 to EGFR decreased, and its binding to intracellular actin was restored to that of the control level." (PMID 30687645, 2018). "Here we demonstrated that CD147, β2AR and Actn4 form stable pre-existing molecular complexes, which are exploited by meningococci for adhesion, signalling and infection." (PMID 28569760, 2017). "Next, we engineered cell lines termed A549-luc-C8-KD-ACTN4s (sh#1 and sh#2), which expressed luciferase (luc), and in which ACTN4 was stably knocked down by infection with a lentivirus-based small hairpin RNA (shRNA)." (PMID 27121206, 2016). "By using confocal microscopy, we also found the cytoskeleton rearrangement in hBMECs during S. suis infection, and similarly, we observed that the infection-activated cellular EGFR competitively recruited ACTN4 from F-actin, which accounts for the infection-induced cytoskeleton disturbance." (PMID 30687645, 2018). "Nevertheless, these results suggest that the HPV genotype, duration of infection and immune reaction may determine the abundance of ACTN4 in the CVF." (PMID 25215525, 2014). "Following infection, changes in expression of Actn4, Aldha1 and Dot1L were examined by qPCR." (PMID 24983472, 2014). "Strikingly, this mechanism operated not only for meningitic E. coli, but also for infections with Streptococcus suis, a Gram-positive meningitis-causing bacterial pathogen, thus revealing a common mechanism hijacked by these meningitic pathogens where EGFR competitively recruits ACTN4." (PMID 30687645, 2018). "During PCN033 infection, EGFR (Dylight 405 labeled in blue) was recruited and more ACTN4 became bound (shown as the color purple), while contrastingly, the co-location of ACTN4 and F-actin disappeared from view in the cells (arrows indicated)." (PMID 30687645, 2018). "Several proteins (bands) were shown to be induced by PCN033 infection, and one at around 100 kDa was identified as ACTN4 (a type of cytoskeleton-associated protein), through mass spectrum (MS) analysis, suggesting that EGFR might recruit additional ACTN4 protein upon PCN033 challenge." (PMID 30687645, 2018). "We also investigated this interaction in hBMECs upon infection with meningitic E. coli K1 strain RS218, and a similar result of increased binding of ACTN4 to EGFR was also observed." (PMID 30687645, 2018). "We also observed similar results in cells undergoing K1 strain RS218 infection, which showed the EGFR-related competitive recruitment of ACTN4 from actin in the cell cytoskeleton." (PMID 30687645, 2018). "Here, by comparing the anti-EGFR immunoprecipitation products from cells with or without infection, we identified ACTN4 as an interacting protein for EGFR." (PMID 30687645, 2018). "However, infection with LR-HPV (HPV-6 and HPV-11) resulted in higher ACTN4 concentrations in the CVF." (PMID 25215525, 2014). "The chemosensitivity of the cells was not changed by infection of shRNA of ACTN4." (PMID 27121206, 2016).
infection (continued). "Although ACTN4 levels did not numerically correlate with the viral loads, an ascending and descending trend could clearly be observed in patients who either started an infection or cleared the virus." (PMID 25215525, 2014). "Comparison of the ACTN4 levels in HPV-infected (both HR- and LR-infections) versus non-infected samples (healthy patients) showed a significant difference, with a p value of 0.009." (PMID 25215525, 2014). "However, our western blotting result showed no significant alteration of the actin from EGFR immunoprecipitates in response to the infection, raising the speculation that this actin protein would be naturally conjugated with EGFR, and this binding might not be attributed to the recruited ACTN4." (PMID 30687645, 2018).
bacterial infection (1 paper, 2014). "These false positives could be the result of an exceptionally high ACTN4-inducing capacity by HPV6 or of an additional viral, fungal, or bacterial infection that also caused an increase of ACTN4 levels in the CVF." (PMID 25215525, 2014).
cardiovascular disease (1 paper, 2019). "Moreover, a recent meta-analysis of 35 GWAS studies reported the association of SNP (rs11083475) in the ACTN4 locus with increased resting heart rate, which may increase cardiovascular disease risk." (PMID 31597446, 2019).
immune disorder (1 paper, 2017). "As regards to the non-syndromic forms, some are related to a still not completely understood underlying immune disorder, while an increasing number is found to be caused by mutations in genes highly expressed in podocytes (e.g. NPHS1, NPHS2, CD2AP, PLCE1, ACTN4, TRPC6, and INF2)." (PMID 28298181, 2017).
ACTN4 also shares sentences with these, for which no sentence is quoted: adenocarcinoma (2 papers); bladder cancer (2); coronary artery disease (2); diabetes (2); glomerulopathies (2); neurodegenerative disease (2); prediabetes (2); sarcoidosis (2); acinic cell carcinoma (1); amelanotic melanoma (1); atrial fibrillation and flutter (1); benign tumors (1); brain tumor (1); breast tumors (1); carcinomas of the pancreas (1); cardiac diseases (1); cardiac dysrhythmias (1); cholangiocarcinoma (1); ciliopathies (1); congestive heart failure (1); cystic kidney disease (1); Denys-Drash syndrome (1); depression (1); Diffuse mesangial sclerosis (1); E. coli infection (1); esophageal squamous cell carcinoma (1); Fabry disease (1); Hearing impairment (1); heart failure (1); hematological disorders (1).
A further 26 diseases each share a sentence with ACTN4 in 1 paper.